BDNF (brain derived neurotrophic factor)
Diseases named in the same sentence as BDNF in open-access papers (continued):
Sharing a sentence is not in itself a finding about the gene and the disease.
neurodegenerative disease (continued). "Furthermore, disruptions in the BDNF-cAMP response element-binding protein (CREB) signaling pathway have been implicated in neurodegenerative diseases, where synaptic loss and memory deficits are prominent consequences of BDNF depletion." (PMID 40726602, 2025). "It has been shown that changes in BDNF levels may be one of the underlying mechanisms of many neurodegenerative diseases and learning and memory disorders." (PMID 40208367, 2025). "These insights provide essential theoretical underpinnings that could pave the way for the development of novel therapeutic strategies aimed at addressing neurodegenerative diseases and respiratory conditions linked to BDNF dysregulation." (PMID 40034284, 2025). "The impairment and death of neurons occur when effective BDNF levels are insufficient or when its binding to TrkB (tyrosine kinase receptor B) and p75 receptors is blocked, which is a major cause of the onset and progression of neurodegenerative diseases." (PMID 40429646, 2025). "Furthermore, various studies have explored the role of BDNF in neurodegenerative diseases and its associated mechanisms." (PMID 40397120, 2025). "As persistent exposure to proinflammatory cytokines is known to influence multiple BDNF‐related signaling pathways, a recent hypothesis postulates that these aberrant BDNF levels may be caused by neuroinflammatory changes in certain neurodegenerative diseases." (PMID 38688895, 2024). "Lower BDNF levels are linked to ageing and neurodegenerative diseases." (PMID 39734666, 2024). "Therefore, roasted AM shows potential as a neuroprotective agent for preventing or treating neurodegenerative diseases, such as Alzheimer’s, linked to BDNF deficiency." (PMID 39594453, 2024). "In addition, impairment of BDNF synthesis is a possible hallmark of numerous neurodegenerative diseases." (PMID 38006577, 2024). "Neurodegenerative diseases are often associated with diminished BDNF levels." (PMID 39935805, 2024). "This neurogenic effect is driven by the upregulation of BDNF signaling, which supports neuronal survival and synaptic resilience, offering a potential buffer against the cognitive deterioration typically linked to neurodegenerative diseases." (PMID 39767653, 2024). "Low levels of BDNF are associated with increased neurodegenerative diseases." (PMID 36978969, 2023). "In that respect, it resembled a neurodegenerative disease associated with a reduction in BDNF." (PMID 38050515, 2023). "Indeed, evaluations of post-mortem brain tissues from patients with neurodegenerative diseases revealed that neuronal degeneration was strictly associated with a decrease in BDNF serum levels." (PMID 37109038, 2023). "Furthermore, the presence of frailty was significantly associated with plasma BDNF levels even after extensive adjustment for confounding factors, including age and neurodegenerative diseases." (PMID 36329115, 2022). "Multiple studies have demonstrated that BDNF has therapeutic potential for promoting axonal regeneration, maintaining synaptic strength, preventing neuron loss in several neurodegenerative disease models, and inducing neuronal redifferentiation in acute CNS injury." (PMID 35814950, 2022). "The loss of BDNF function has been implicated in many neurodegenerative diseases." (PMID 35418836, 2022). "Thus, miR-126 can provide a crucial bridge between metabolic disturbances and neurotoxicity through the association with BDNF and their common signaling cascades in the pathogenesis of neurodegenerative disease, including PD and AD." (PMID 32944919, 2021). "Previous reports obtained from postmortem brains, clinical studies, and animal experiments strongly suggested that reduced brain-derived neurotrophic factor (BDNF) expression levels in the brain are associated with neurodegenerative diseases and neuropsychiatric disorders." (PMID 34977362, 2021).
neurodegenerative disease (continued). "We therefore hypothesized that combined BDNF and TrkB replacement would demonstrate superior efficacy compared to receptor or ligand alone and assessed this in two models of neurodegenerative disease known to be associated with reduced axonal transport." (PMID 33789891, 2021). "The disruption of the BDNF-TrkB signaling pathway is implicated in neurodegenerative diseases." (PMID 31156376, 2019). "Aging or neurodegenerative diseases are associated with a decrease in BDNF expression." (PMID 31703409, 2019). "Considering the decreased levels of BDNF in the ageing hippocampus, several studies have suggested a mechanistic role for this neurotrophic factor in age-related hippocampal dysfunction, memory weakening and increased risk of neurodegenerative diseases." (PMID 31188781, 2019). "Given the age-sex interaction on serum BDNF levels and the known association between BDNF and gonadal hormones, research is warranted to delineate the effects of the latter interaction on the risk of psychiatric and neurodegenerative diseases." (PMID 21247257, 2012). "Moreover, BDNF levels are thought to play an important role in susceptibility of non-neurodegenerative diseases." (PMID 23210531, 2012). "Along these lines, BDNF levels in humans have been linked to a wide variety of brain diseases, among which neuropsychiatric and neurodegenerative diseases." (PMID 21247257, 2012). "Indeed, lower levels of BDNF are implicated in cognitive dysfunction in neurodegenerative diseases." (PMID 36451805, 2022). "Moreover, it is reported that lower BDNF levels are associated with neurodegenerative diseases." (PMID 34944391, 2021). "The expression of BDNF has also been implicated in the effect of many neurological disorders, which is also involved in the expression of neuronal plasticity genes, so it is now also believed that neurodegenerative diseases are frequently associated with a loss of synapses and neurons." (PMID 34975553, 2021). "This highlights that it is difficult to establish a causal link between BNDF downregulation and the development of this neurodegenerative disease because the pathology is accompanied by a loss of cell density and dendritic spines that could secondarily affect BDNF levels." (PMID 31440144, 2019). "Considering the diverse functions of BDNF in neurogenesis and memory persistence, our results suggest that Cf-hGP treatment might have beneficial effects in controlling ER stress-induced cognitive dysfunction and neurodegenerative diseases associated with age." (PMID 30875947, 2019). "Gene dosage studies, with sufficient power will compare all three genotypes (Val/Val, Val/Met, and Met/Met) and may potentially reveal whether any specific phenotypic effects in neurodegenerative disease pathology are truly associated with the BDNF polymorphism." (PMID 29896439, 2018). "Additionally, BDNF could promote survival of basal ganglia neurons and its progressive loss had been shown in neurodegenerative diseases such as HD." (PMID 27738307, 2016). "The brain-derived neurotrophic factor (BDNF) is a neurotrophic factor that improves neuronal function in neurodegenerative diseases." (PMID 41528544, 2026). "This integrated perspective reconciles similarities and differences among AD, PD, and HD and underscores the importance of preserving BDNF–ERK signaling integrity as a unifying therapeutic strategy across neurodegenerative diseases." (PMID 41596628, 2026). "Individuals with neurodegenerative diseases, including AD, have significantly lower levels of BDNF in blood serum (measuring bound and unbound BDNF) than their healthy counterparts." (PMID 40405549, 2025). "This is particularly relevant to neurodegenerative diseases, as BDNF supports neuronal survival and boosts cognitive function." (PMID 40427596, 2025). "These agents also improved memory performance and represent a unique, scalable means of augmenting BDNF availability in neurodegenerative disease." (PMID 40362507, 2025).
neurodegenerative disease (continued). "For example, brain‐derived neurotrophic factor (BDNF), a crucial molecule with multiple implications in memory, ageing and neurodegenerative diseases, is released from presynaptic dense‐core vesicles in an activity‐dependent manner." (PMID 39367860, 2025). "The next section will explore how BDNF supports neuroprotection and regenerative mechanisms, offering new hope for treating injury and neurodegenerative diseases." (PMID 40362507, 2025). "Intranasal delivery has been used in clinical studies to deliver small-molecule agents to the brain, such as nerve growth factor (NGF) and brain-derived neurotrophic factor (BDNF), thus treating neurodegenerative diseases." (PMID 40606141, 2025). "In line with this, previous studies have reported the neuroprotective role of curcumin, particularly in neurodegenerative diseases, suggesting that it can regulate BDNF and the phosphatidylinositol 3 kinase (PI3k)/protein kinase B (Akt) signaling pathways." (PMID 40361833, 2025). "In summary, HIFN is a promising TrkB receptor activator, as a potential alternative to BDNF therapy in the realm of treating neurodegenerative diseases." (PMID 40027732, 2025). "At the metabolomic level, it has been found to have neuroprotective effects against neurodegenerative diseases by increasing the secretion of neurotrophins, such as brain-derived neurotrophic factor and nerve growth factor." (PMID 39997711, 2025). "As a pharmacological drug, LDL intervenes with the BDNF mechanism in the body; now in conjunction with these new pharmacological interventions, a new paradigm for treating neurodegenerative disease is warranted." (PMID 40362507, 2025). "In neurodegenerative diseases, mollugin exhibits significant neuroprotection in endothelial and hippocampal experimental models through the regulation of the BDNF/TrkB and GLP-1R signaling pathways." (PMID 41465430, 2025). "BDNF has been widely recognized for its neuroprotective effects, particularly in models of neurodegenerative diseases including PD." (PMID 40564225, 2025). "It has been identified that BDNF plays as a regulator of various forms of neuroplasticity in neurodegenerative disease processes including focal ischemic brain injury, tau pathology, which contributes to AD." (PMID 41267965, 2025). "The delicate equilibrium between BDNF and proBDNF is critical in regulating neuronal apoptosis in neurodegenerative diseases." (PMID 40430064, 2025). "Decreased circulating BDNF has also been reported in neurodegenerative diseases, where it coincides with an upregulation of pro-inflammatory cytokines in the brain, ultimately contributing to neuronal loss." (PMID 41155372, 2025). "These pathways were, in general, shared across all neurodegenerative diseases, even though the major overlap was found for the synaptic functions (BDNF, CCL2, ACHE, GFAP, NEFH or NEFL) and microglia pathways (TREM2, IL13, IL6R IFNG)." (PMID 41250190, 2025). "BDNF is an important target for neurodegenerative disease (ND) treatment since it regulates neuronal survival, synaptic plasticity, neurogenesis, and neuroprotection." (PMID 40149774, 2025). "In recent years, the administration of exogenous BDNF has been explored as a therapeutic strategy for neurodegenerative diseases." (PMID 40697272, 2025). "The interaction between the BDNF and TRkB enzyme enhances neurogenesis, synaptic plasticity, and neuroprotection, making it a promising therapeutic target for mental and neurodegenerative diseases like PD." (PMID 40227469, 2025). "A number of studies have demonstrated that the altered expression and action of neurotrophic factors and their receptors, such as BDNF/TrkB signaling, is involved in the pathogenesis of neurodegenerative diseases." (PMID 38397748, 2024). "Subsidiary to this concept, diverse studies specified that BDNF serum level is functionally altered in different neurodegenerative diseases." (PMID 38752280, 2024).
neurodegenerative disease (continued). "The relationship between BDNF, its TrkB receptor, neurodegenerative disorders, and neuroprotection is well documented, with diminished BDNF levels observed in various neurodegenerative diseases and correlating with disease severity." (PMID 38667284, 2024). "A recent publication reports the potential therapeutic effect of increasing BDNF in various neurodegenerative diseases." (PMID 39726067, 2024). "Other studies have highlighted that DHA stimulates the release of brain-derived neurotrophic factor (BDNF) and is able to control morphology and synaptogenesis, so acting as a potential therapeutic agent in neurodegenerative diseases." (PMID 39459191, 2024). "There is a substantial body of data linking BDNF to neuronal plasticity, repair, and survival, as well as to neurotransmitter release, and patients with neurodegenerative diseases frequently have lower BDNF levels in their brain." (PMID 38688895, 2024). "This review examines the impact of physical exercise on the regulation of brain-derived neurotrophic factor (BDNF) in individuals with neurodegenerative diseases, focusing on brain plasticity and neuroprotection." (PMID 39935805, 2024). "Brain-derived neurotrophic factor (BDNF) is an important neurotrophic factor for protecting neurodegenerative diseases." (PMID 39569182, 2024). "A prospective research study focusing on clinical endpoints of neurodegenerative diseases is needed to assess an importance of the presented BDNF findings." (PMID 38671019, 2024). "The potential of BDNF to access the cerebrospinal fluid with appealed concentration and prompt a healing reflex considers an essential therapeutic approach for neurodegenerative diseases." (PMID 37287291, 2024). "Several studies indicate impaired maturation and a decreased mature-BDNF/pro-BDNF ratio as early indicators of neurodegenerative disease development." (PMID 38182767, 2024). "Furin also affects neuronal tissueby promoting the conversion of brain-derived neurotrophicfactor (BDNF) from pro-BDNF to its mature form, potentiallyinfluencing neurodegenerative diseases." (PMID 39944797, 2024). "The ability of I3C to affect OS, inflammation and apoptosis, and to modulate brain-BDNF, is an important element in the pathophysiology of neurodegenerative diseases, and is largely responsible for its neuroprotective benefits." (PMID 39061415, 2024). "The neurodegenerative diseases have been associated with the dysregulation of AKT and CREB that will impact BDNF gene expression." (PMID 39569182, 2024). "In neurodegenerative diseases, synthetic mRNA can be used to produce neuroprotective factors like brain-derived neurotrophic factor (BDNF) or glial cell line-derived neurotrophic factor (GDNF), supporting neuronal health and survival." (PMID 39684324, 2024). "Animal models have contributed to elucidating neuroprotective molecular pathways activated through exercise, suggesting neuroinflammation, synaptic plasticity, and BDNF as key pathways capable of attenuating the phenotypes of neurodegenerative diseases." (PMID 38110646, 2024). "Ladostigil prevents the development of neurodegenerative diseases by enhancing BDNF/TrkB signalling via numerous molecular signalling." (PMID 38752280, 2024). "It is known that the brain-derived neurotrophic factor (BDNF) has a neuroprotective effect in various neurodegenerative diseases." (PMID 39408863, 2024). "In PD and other neurodegenerative diseases, the conversion of proBDNF to BDNF is inhibited mainly in the striatum and hippocampus leading to an imbalance of proBDNF BDNF expression." (PMID 38752280, 2024). "The roles of physical exercise and BDNF have become central to understanding neurodegenerative disease modulation." (PMID 39935805, 2024). "The cognitive and memory functions are affected by the neurodegenerative diseases through the low BDNF and CREB signaling." (PMID 38261905, 2024).
neurodegenerative disease (continued). "Ginsenoside Rh1 increases the survival rate of hippocampal cells and activates BDNF, which regulates nerve cells, confirming its potential as a therapeutic agent for neurodegenerative diseases." (PMID 37686071, 2023). "It is critical for neurogenesis and the development and functional maintenance of the nervous system, and BDNF levels are found to be reduced in patients or animal models with neurodegenerative diseases such as AD and HD." (PMID 38069318, 2023). "BDNF expressed in the CNS and blood has been found to be involved in the neuropathology of various neurodegenerative diseases, including AD." (PMID 38053647, 2023). "Upregulation of the BDNF/TrkB system plays an important role in determining the protective effects of traditional medicine in neurodegenerative disease models." (PMID 36983803, 2023). "The decreased level of BDNF influences the neurodegenerative disease related to the cerebral cortex and directly relates to the gut-brain axis, which triggers other diseases too." (PMID 37110506, 2023). "BDNF is a well-known indicator of synaptic function regulation, neural survival, and differentiation, and can have therapeutic implications in various neurodegenerative diseases." (PMID 36979237, 2023). "Researchers have been investigating the relationship between BDNF levels and activity and the occurrence and outcome of neurodegenerative diseases." (PMID 37450039, 2023). "Considerable evidences highlighted that Fndc5/irisin mediates the expression of brain-derived neurotrophic factor (BDNF) in hippocampal neurons, and has neuroprotective effects against neurodegenerative diseases and neuroinflammation." (PMID 36823656, 2023). "The mechanism of olfactory disturbance in neurodegenerative diseases involves neurotoxic effects, which include atrophy of hippocampal cells due to abnormally low concentrations of neurotrophic factors, including BDNF." (PMID 37109038, 2023). "A single-nucleotide polymorphism in the pro-region of the human BDNF gene, which results in a valine (Val)-to-methionine (Met) substitution called BDNF Val66Met, is considered to influence the cognitive function in degenerative diseases." (PMID 36850004, 2023). "Overall, for these reasons, understanding in detail BDNF’s role in the brain can be instrumental in developing new therapeutic strategies to counteract memory impairment in neurodegenerative diseases." (PMID 37109038, 2023). "In conclusion, our study establishes a biochemical basis for understanding the formation of the ARMS/Syt4 complex, which is important for gaining insight into the mechanisms of the regulation of BDNF secretion and neurodegenerative diseases." (PMID 38069318, 2023). "A low level of BDNF in peripheral blood or CNS and insufficient transformation of pro-BDNF into mature BDNF (mBDNF) have been found to be involved in the pathogenesis of neurodegenerative diseases." (PMID 36827132, 2023). "Over the last years, many research efforts have focused on developing BDNF mimetics with suitable pharmacological properties in order to be used as new therapeutics against neurodegenerative diseases." (PMID 37755078, 2023). "Earlier studies have suggested lower BDNF concentrations in patients with neurodegenerative diseases such as Alzheimer60, and Parkinson61." (PMID 37596403, 2023). "To date, various strategies based on BDNF administration are designed to restore BDNF function in neurodegenerative diseases." (PMID 36631409, 2023). "Given its function in synaptic repair, BDNF is considered a strategy for repair in neurodegenerative diseases." (PMID 36979272, 2023). "BDNF trophic support has been proposed as a therapeutic intervention to delay or prevent the onset and progression of neurodegenerative diseases." (PMID 36829435, 2023).